SFXN1 (sideroflexin 1)
Description:
Amino acid transporter importing serine, an essential substrate of the mitochondrial branch of the one-carbon pathway, into mitochondria. Mitochondrial serine is then converted to glycine and formate, which exits to the cytosol where it is used to generate the charged folates that serve as one-carbon donors. May also transport other amino acids including alanine and cysteine.
Synonyms: FLJ12876; SLC56A1; TCC
Tractability: Antibody: UniProt predicts a signal peptide or a membrane-spanning region. PROTAC: ubiquitination databases record sites on it; its protein half-life has been measured.
Gene: Protein-coding gene on chromosome 5 (175,477,062 to 175,529,742, forward strand). Ensembl gene ENSG00000164466.
Subcellular location: Mitochondrion inner membrane
Subcellular location (Human Protein Atlas): Mitochondria
Gene Ontology:
Molecular function: L-alanine transmembrane transporter activity; L-serine transmembrane transporter activity; protein binding; transmembrane transporter activity; monoatomic ion transmembrane transporter activity
Biological process: L-alanine transport; L-serine transport; one-carbon metabolic process; serine import into mitochondrion; monoatomic ion transmembrane transport; monoatomic ion transport; transmembrane transport
Cellular component: mitochondrial inner membrane; mitochondrion; membrane
Genetic constraint (gnomAD): Loss-of-function variants: 32 observed, 40.69 expected, observed/expected ratio (o/e) 0.79, 90% interval 0.59 to 1.06. The upper end of that interval is the gene's LOEUF score, 1.06, which puts it in group 4 of 6, group 1 being the genes least tolerant of losing a copy. Missense variants: 393 observed, 415.33 expected, observed/expected ratio (o/e) 0.95, 90% interval 0.87 to 1.03. Synonymous variants: 134 observed, 148.96 expected, observed/expected ratio (o/e) 0.9, 90% interval 0.78 to 1.04.
Homologues: Orthologues: chimpanzee SFXN1 (99% identical), macaque SFXN1 (99% identical), pig SFXN1 (97% identical), guinea pig SFXN1 (96% identical), rat Sfxn1 (96% identical), mouse Sfxn1 (95% identical), tropical clawed frog sfxn1 (91% identical), zebrafish sfxn1 (84% identical), dog SFXN1 (81% identical), rabbit SFXN1 (79% identical), Drosophila melanogaster Sfxn1-3 (55% identical), Caenorhabditis elegans sfxn-1.5 (55% identical), and 4 more. Paralogues in human: SFXN3 (76% identical), SFXN2 (55% identical), SFXN5 (39% identical), SFXN4 (21% identical).
Diseases named in the same sentence as SFXN1 in open-access papers:
SFXN1 is named in the same sentence as 34 diseases in open-access papers, as found by Europe PMC text mining. Sharing a sentence is not in itself a finding about the gene and the disease. The quoted sentences say what the papers report.
breast cancer (5 papers, 2022 to 2026). A primary or metastatic malignant neoplasm involving the breast. "Numerous cancers, including colorectal, liver, and breast cancers, exhibit abnormal expression of SFXN1, indicating that SFXN1 has a shared carcinogenic function across tumor types." (PMID 41399448, 2026). "Similarly, in breast cancer, the study demonstrated that the overexpression of SFXN1 is correlated with poor prognosis and aggressive tumor behavior." (PMID 41399448, 2026). "Analysis of the TCGA database suggested that the expression of SFXN1, a member of the SFXN family of genes, was significantly upregulated in several types of cancer, including lung cancer, hepatocellular carcinoma, and breast cancer, as compared to paracancerous tissues." (PMID 38233752, 2024). "Thus, the absence of SERAC1 in our SFXN1 interactome may be explained by either the different cell lines used (mammary tumor cells versus kidney embryonic cells) or a labile interaction that could not be detected with endogenous SFXN1." (PMID 36138777, 2022).
sideroblastic anemia (5 papers, 2020 to 2023). "Mice mutant for Sfxn1 displayed sideroblastic anemia, microcytic anemia and hypochromic erythrocytes." (PMID 33494450, 2021). "Sideroflexin 1 (SLC56A1/SFXN1) has been described as the gene whose defects are responsible for the flexed-tail mouse phenotype with sideroblastic anemia." (PMID 33260588, 2020). "Furthermore, previous research discovered that SFXN1 is closely related to pathologic mitochondrial iron accumulation, which led to sideroblastic anemia." (PMID 35979359, 2022).
lung adenocarcinoma (3 papers, 2023 to 2025). A carcinoma that arises from the lung and is characterized by the presence of malignant glandular epithelial cells. "This study aims to identify and assess Sideroflexin1 (SFXN1), an unprecedented mitochondrial gene, as a potential prognostic biomarker for lung adenocarcinoma (LUAD)." (PMID 38233752, 2024). "Additionally, SFXN1 upregulation has been observed in certain types of cancers, such as lung adenocarcinoma and triple‐negative breast cancer, and is associated with poor prognosis." (PMID 40420406, 2025).
lung carcinoma (3 papers, 2024 to 2026). "SFXN1 has been implicated in mitochondrial iron metabolism and immune response modulation in other cancer types, such as lung cancer, but this study expands its importance to immune infiltration in HNSC, particularly highlighting its link with CD4+ T cells and possible impact on clinical outcomes." (PMID 41399448, 2026). "We validated the prognostic value of SFXN1 in LUAD using our clinical data with the hope of providing useful insights into the mitochondrial genetic etiology of lung cancer." (PMID 38233752, 2024).
Alzheimer disease (2 papers, 2025). A progressive, neurodegenerative disease characterized by loss of function and death of nerve cells in several areas of the brain leading to loss of cognitive function such as memory and language. "Although previous studies have linked decreased SFXN1 expression in the brain to Alzheimer's disease and Parkinson's disease, and SFXN1 downregulation has been associated with nonviral hepatocellular carcinoma, the role of SFXN1 in neuronal death remains unclear." (PMID 40420406, 2025). "SFXN1 and SFXN3 are downregulated in both Alzheimer’s disease and PD, both conditions marked by mitochondrial dysfunction." (PMID 40894005, 2025).
anemia (2 papers, 2023 to 2025). A reduction in the number of red blood cells, the amount of hemoglobin, and/or the volume of packed red blood cells. "Sfxn1 (sideroflexin-1) was originally identified as the gene mutated in a mouse mutant with anemia and axial skeletal abnormalities, however, its molecular roles remained unclear." (PMID 37296228, 2023). "For example, SFXN1 is required for erythroid cell development, and SFXN1 knockout leads to hypochromic anemia in zebrafish." (PMID 40420406, 2025).
cardiac hypertrophy (2 papers, 2021 to 2023). "Apelin-13-induced mitochondrial iron excess is reversed by inhibiting SFXN1 and NCOA4 expression, which it also mitigates cardiac hypertrophy." (PMID 38102663, 2023). "This indicates that NCOA4 functions upstream of SFXN1 and implicates NCOA4-mediated autophagy and ferroptosis in the development of cardiac hypertrophy." (PMID 38102663, 2023). "How NCOA4 could upregulate SFXN1 remains unanswered, as well as the role of SFXN1 and the other SFXN/SLC56 transporters in cardiac hypertrophy." (PMID 33494450, 2021).
glioma (2 papers, 2016 to 2025). A benign or malignant brain and spinal cord tumor that arises from glial cells (astrocytes, oligodendrocytes, ependymal cells). "SFXN1 affects mitochondrial function and iron transport and may also modulate tumor progression in gliomas, thus influencing survival." (PMID 39423857, 2025).
head and neck squamous cell carcinoma (2 papers, 2023 to 2026). A squamous cell carcinoma that arises from any of the following anatomic sites: lip and oral cavity, nasal cavity, paranasal sinuses, pharynx, larynx, and salivary glands. "The results revealed that SFXN1 was significantly overexpressed in head and neck squamous cell carcinoma and markedly upregulated in KB cells compared with controls." (PMID 41399448, 2026). "It has been reported that SFXN1 is overexpressed in head and neck squamous cell carcinoma and that high SFXN1 expression in this context is significantly associated with poor prognosis." (PMID 37020524, 2023).
Sepsis (2 papers, 2022 to 2025). Sepsis is defined as life-threatening organ dysfunction caused by a dysregulated host response to infection. "SFXN1 has been implicated in sepsis‐induced cardiac injury and acute lung injury by modulating ferritinophagy‐mediated ferroptosis." (PMID 40420406, 2025). "In the pathological states (sepsis, inflammation, etc.), elevated Fe2+ stimulates the accumulation of sideroflexin 1 (SFXN1) to locate in mitochondrial membrane, which subsequently transports Fe2+ into mitochondria, triggering the production of mitochondrial ROS and ferroptosis." (PMID 36182901, 2022).
brain infarction (1 paper, 2025). Tissue necrosis in any area of the brain, including the cerebral hemispheres, the cerebellum, and the brain stem. "After cerebral ischemia/reperfusion (I/R), the expression of SFXN1 is upregulated in both neurons and microglia, exacerbating brain infarction." (PMID 40420406, 2025). "Virus‐mediated knockdown of SFXN1 in vivo reduced brain infarction after ischemic stroke." (PMID 40420406, 2025).
Cerebral ischemia (1 paper, 2025). Restriction of arterial blood supply to the brain associated with insufficient oxygenation to support the metabolic requirements of the tissue. "However, the role of SFXN1 in cerebral ischemia–reperfusion (I/R)‐induced neuronal death remains unclear." (PMID 40420406, 2025).
head and neck cancer (1 paper, 2026). A primary or metastatic malignant neoplasm affecting the head and neck. "This study expands the investigation of SFXN1 in head and neck cancer, although its specific role in OSCC biology requires further clarification." (PMID 41399448, 2026).
ischemic stroke (1 paper, 2025). A stroke disorder caused by obstruction of blood flow to the brain, due to thrombotic (local blood clot formation) or embolic (due to a blood clot or other material traveling from another site) event. "In this study, we found that SFXN1 expression was upregulated after cerebral I/R and that knocking down SFXN1 in vivo reduced the brain infarct volume following ischemic stroke." (PMID 40420406, 2025). "To examine the effects of SFXN1 on ischemic stroke, we injected AAVs into the cortex of mice to knock down SFXN1 and assessed its impact on the brain infarct volume after ischemic stroke." (PMID 40420406, 2025). "However, the role of SFXN1 in ischemic stroke remains unknown." (PMID 40420406, 2025).
leukemia (1 paper, 2022). A malignant (clonal) hematologic disorder, involving hematopoietic stem cells and characterized by the presence of primitive or atypical myeloid or lymphoid cells in the bone marrow and the blood. "SFXN1 is expressed in a number of cancer cells, with the highest expression in leukemia and lymphoma." (PMID 36138824, 2022).
liver cancer (1 paper, 2023). An epithelial or non-epithelial malignant neoplasm that arises from the liver. "SFXN1 was generally expressed in HCC cell lines at both the mRNA and protein levels, and the protein expression level of SFXN1 was downregulated in human liver cancer cell lines compared to human hepatocytes." (PMID 37296228, 2023). "We next assessed the expression level of SFXN1 in 26 human HCC cells using publicly available transcriptome data from the Cancer Cell Line Encyclopedia and conducting Western blot analysis of immortalized but not transformed human hepatocytes HuSE2 and six human liver cancer cell lines." (PMID 37296228, 2023).
lymph node metastasis (1 paper, 2024). "The results showed that SFXN1 expression was significantly higher in patients with locally advanced stage (P < 0.0001), lymph node metastasis (P < 0.0001), and larger tumor size (P = 0.0123) than in patients with early-stage disease, no lymph node metastasis, and T1 stage disease." (PMID 38233752, 2024).
neuroblastoma (1 paper, 2025). Neuroblastoma (NB) is the most common solid, extracranial childhood tumor. "In addition, the knockdown of SFXN1 in SH‐SY5Y cells (a neuroblastoma cell line widely used cell lines in neurosciences) resulted in increased cell viability and decreased LDH release." (PMID 40420406, 2025).
non-small cell lung carcinoma (1 paper, 2024). A group of at least three distinct histological types of lung cancer, including non-small cell squamous cell carcinoma, adenocarcinoma, and large cell carcinoma. "Our study also demonstrated that patients with high SFXN1 expression had a significantly higher TMB, which is consistent with previous findings linking high TMB to a poor prognosis for non-small cell lung cancer." (PMID 38233752, 2024).
oral squamous cell carcinoma (1 paper, 2026). "This study provides substantial evidence supporting SFXN1 as a promising biomarker in oral squamous cell carcinoma (OSCC)." (PMID 41399448, 2026).
ovarian carcinoma (1 paper, 2026). A malignant neoplasm originating from the surface ovarian epithelium. "Previous reports in other cancer types, notably ovarian cancer, have consistently demonstrated that SFXN1 plays a pivotal role in supporting tumor growth, metabolic regulation, and mitochondrial function." (PMID 41399448, 2026).
X-linked sideroblastic anemia (1 paper, 2021). "Since mice lacking Sfxn1 present similar features to that observed in human syndromes caused by a lack of pyridoxine or ALAS2 mutation (X-linked sideroblastic anemia), it was also proposed that Sfxn1 transports pyridoxine (B6 vitamin) inside the mitochondria." (PMID 33494450, 2021).
tumor (11 papers, 2022 to 2026). "Our data revealed that high SFXN1 expression was strongly associated with larger tumor sizes (P = 0.0055), lymph node involvement (P = 0.0096), distant organ metastasis (P = 0.0322), and advanced TNM staging (P < 0.0001) among these patients." (PMID 38233752, 2024). "While survival analysis did not reveal significant associations with patient outcomes (HR = 1.1, p = 0.47), the consistent overexpression of SFXN1 in tumor tissues and its associations with certain tumor characteristics suggest biological functions that merit further investigation." (PMID 41399448, 2026). "SFXN1 has been linked to mitochondrial iron metabolism and tumor growth in other malignancies." (PMID 41399448, 2026). "The absence of stage-specific expression differences indicates that SFXN1 overexpression occurs independently of tumor stage progression." (PMID 41399448, 2026). "Mechanistically, SFXN1 was found to influence the tumor immune microenvironment by modulating the infiltration of immune cells, including T cells and macrophages, and activating inflammatory and oncogenic pathways." (PMID 41399448, 2026). "Compared with that in adjacent normal tissues, SFXN1 was notably overexpressed in primary tumor tissues, indicating its potential involvement in HNSC pathogenesis." (PMID 41399448, 2026). "report that SFXN1 knockdown significantly reduced cell proliferation and migration in vitro, potentially by inhibiting ERK phosphorylation and CCL20 expression; in vivo, targeting SFXN1 decreased Tregs infiltration and suppressed tumor growth." (PMID 41415540, 2025). "We found that SFXN1 expression was correlated with clinical stage, tumor size, lymph node invasion, and distant metastasis." (PMID 38233752, 2024). "Our study also found that tumor purity was higher in LUAD patients with SFXN1 overexpression, indicating that there were fewer infiltrating immune cells in the tumor microenvironment." (PMID 38233752, 2024). "We examined the expression of SFXN1 in the tumor microenvironment by analyzing single-cell sequencing data from an online database of LUAD patients." (PMID 38233752, 2024). "SFXN1 was markedly upregulated at both mRNA and protein levels in LUAD, and high expression of SFXN1 were correlated with larger tumor size, positive lymph node metastasis, and advanced clinical stage." (PMID 38233752, 2024). "In both groups, the protein expression level of SFXN1 was downregulated in tumor tissues compared to adjacent liver tissues, with a more pronounced decrease observed in the low expression group." (PMID 37296228, 2023). "In order to examine in vivo effects of SFXN1-KO on lipotoxicity, we subcutaneously injected the HuH7-Control and HuH7-SFXN1-KO cells into nude mice, and fed the tumor-bearing mice with either normal diet (ND) or high-fat diet (HFD)." (PMID 37296228, 2023). "SFXN1 was easily detected with Western blot in cell extracts from human transformed or tumor-derived cell lines." (PMID 36138777, 2022). "LPs could significantly normalize serine levels by modulaitng the synthesis of serine in gut microbiota and its SFXN1-mediated transport in tumor cells." (PMID 41625335, 2026). "The correlation with tumor grade further strengthened this association, as patients with higher histological grades (grades 3 and 4) presented significantly greater SFXN1 expression than did those with lower grades and normal tissues, supporting its role in aggressive tumor phenotypes." (PMID 41399448, 2026). "Immune cell correlation analyses revealed that SFXN1 may influence by the tumor immune microenvironment." (PMID 41399448, 2026). "SFXN1 expression was associated with tumor grade and nodal metastasis, although no significant stage-specific differences were observed." (PMID 41399448, 2026).